PLEKHF2 (pleckstrin homology and FYVE domain containing 2)
Description:
May play a role in early endosome fusion upstream of RAB5, hence regulating receptor trafficking and fluid-phase transport. Enhances cellular sensitivity to TNF-induced apoptosis.
Synonyms: EAPF; Phafin2; ZFYVE18; FLJ13187
Tractability: Antibody: UniProt places it where antibodies can reach, with high confidence. PROTAC: ubiquitination databases record sites on it; its protein half-life has been measured.
Gene: Protein-coding gene on chromosome 8 (95,115,642 to 95,156,698, forward strand). Ensembl gene ENSG00000175895.
Subcellular location: Early endosome membrane; Endoplasmic reticulum
Gene Ontology:
Molecular function: protein binding; phosphatidylinositol binding; metal ion binding
Biological process: endosome organization; endosome to lysosome transport
Cellular component: early endosome membrane; endoplasmic reticulum; transport vesicle; early endosome; cytoplasmic vesicle; endomembrane system
Genetic constraint (gnomAD): Loss-of-function variants: 4 observed, 14.99 expected, observed/expected ratio (o/e) 0.27, 90% interval 0.13 to 0.61. The upper end of that interval is the gene's LOEUF score, 0.61, which puts it in group 2 of 6, group 1 being the genes least tolerant of losing a copy. Missense variants: 201 observed, 325.56 expected, observed/expected ratio (o/e) 0.62, 90% interval 0.55 to 0.69. Synonymous variants: 90 observed, 109.69 expected, observed/expected ratio (o/e) 0.82, 90% interval 0.69 to 0.98.
Homologues: Orthologues: chimpanzee PLEKHF2 (100% identical), macaque PLEKHF2 (99% identical), dog PLEKHF2 (99% identical), pig PLEKHF2 (98% identical), mouse Plekhf2 (98% identical), rat Plekhf2 (97% identical), guinea pig PLEKHF2 (97% identical), tropical clawed frog plekhf2 (85% identical), zebrafish plekhf2 (83% identical), Drosophila melanogaster rush (63% identical), Caenorhabditis elegans ZK632.12 (57% identical). Paralogues in human: PLEKHF1 (55% identical), ZFYVE26 (28% identical), ZFYVE16 (24% identical), ZFYVE28 (22% identical), RUFY1 (20% identical), RUFY2 (20% identical), ZFYVE1 (20% identical), PLEKHM2 (18% identical), RUFY3 (16% identical), SNX29 (15% identical), RUNDC3A (12% identical), RUNDC3B (11% identical), and 1 more.
Diseases named in the same sentence as PLEKHF2 in open-access papers:
PLEKHF2 is named in the same sentence as 9 diseases in open-access papers, as found by Europe PMC text mining. Sharing a sentence is not in itself a finding about the gene and the disease. The quoted sentences say what the papers report.
prostate carcinoma (2 papers, 2021 to 2022). A carcinoma that arises from epithelial cells of the prostate gland. "E. Shamsara and J. Shamsara have confirmed that the amplification of the PLEKHF2 gene is related to the decreased survival of patients with prostate cancer." (PMID 34777635, 2021). "Even the combination of the five genes, including LARP4B, PLEKHF2, SMC4, SLC45A3 and NO6632,39,44,45,48,51, whose clinical relevance and prognostic implications were observed in prostate cancer, had very limited prediction strength for BCR and RFS (not reported in the Results section)." (PMID 35732666, 2022).
aneurysm (1 paper, 2021). Bulging or ballooning in an area of an artery secondary to arterial wall weakening. "Besides, Fibroblast Growth Factor Receptor-Like 1 (FGFRL1) and Pleckstrin Homology and FYVE Domain Containing 2 (PLEKHF2) may affect the transportation of intracellular substances to promote aneurysm formation, through the hsa_circ_0005073/hsa_circ_0081968/hsa-miR-107 regulated axis." (PMID 34777635, 2021).
glaucoma (1 paper, 2022). Increased pressure in the eyeball due to obstruction of the outflow of aqueous humor. "Plekhf2 has not been previously associated with IOP or glaucoma." (PMID 36793389, 2022).
PLEKHF2 also shares sentences with these, for which no sentence is quoted: cancer (3 papers); breast cancer (1); hepatocellular carcinoma (1); liver cancer (1); pancreatic cancer (1); Salmonella Infections (1).